CP (ceruloplasmin)
Diseases named in the same sentence as CP in open-access papers (continued):
Sharing a sentence is not in itself a finding about the gene and the disease.
cancer (continued). "This suggests a specific phenotype for R5 and MCF7 cell lines termed here as the cancer phenotype of the iron homeostasis pathway (CP-IHP)." (PMID 28166223, 2017). "The iP has emerged as a promising therapeutic target for the treatment of autoimmune disorders and cancer; however, it is not well understood how the substrate specificities of the iP and cP diverge." (PMID 29182146, 2017). "Since Geminin has been shown to be involved in regulation of stem cells and cancer cells, CP-Geminin is expected to be useful for elucidating the role of Geminin in stem cells and cancer cells, and for manipulating their activity." (PMID 27195810, 2016). "Ceruloplasmin, Complement factor B or complement component C3 had already been reported elevated in hepatocarcinoma and other cancers." (PMID 25826090, 2015). "Consistent with our mass spectrometry data, CP was significantly up-regulated in the cancer patients." (PMID 26133466, 2015). "Urine samples from a total of 60 patients and 60 controls were analyzed, and a significant up-regulation of CP was found in the cancer patients (p = 0.0014)." (PMID 26133466, 2015). "By contrast, a total of 36 cancer patients and 18 controls showed a slight increase in CP in the serum (p = 0.063)." (PMID 26133466, 2015). "Accordingly, the protein synthesis inhibitor cycloheximide significantly protected cancer cells from CP-induced cell death, suggesting that protein synthesis machinery was involved." (PMID 24980813, 2014). "Roles for ceruloplasmin have been suggested in cancer-related processes, including angiogenesis and neovascularization." (PMID 23251472, 2012). "Furthermore, the inhibitory impact of chemotherapy on the impairment of the immune system establishes advantageous circumstances for the use of combination therapy with CP, so enhancing the reactive immune response against malignancies." (PMID 39981238, 2025). "Below we present our principal results, regarding C1q’s CP-independent role in cancer." (PMID 40370471, 2025). "Moreover, in cancer and inflammation, plasma Cu and ceruloplasmin concentrations were raised, and the rates of synthesis and secretion of ceruloplasmin by the liver were enhanced." (PMID 38250988, 2024). "Next, we explored the possibility that Long non-coding RNA (lncRNA) LINC02936/SIX1/CP axis may be a key pathway for inhibiting ferroptosis and promoting cancer progression in EC." (PMID 38385087, 2024). "However, research has demonstrated that ceruloplasmin, the primary protein that binds to copper, can potentially stimulate the growth of new blood vessels and is also found in higher levels in cancer cells." (PMID 38792632, 2024). "Thus, we explored that long non-coding RNA (lncRNA) LINC02936/SIX1/CP axis is a key pathway for suppressing ferroptosis and promoting cancer progression in EC." (PMID 38385087, 2024). "First, correlation analysis determined significant correlation of 18 proteins with cancer-associated inflammation, including 9 proteins correlated positively such as C8A, A2GL, and ceruloplasmin (CERU), while another 9 proteins including retinol-binding protein 4 (RET4) were correlated negatively." (PMID 38911905, 2024). "Thus, CP/CPPS exhibits molecular changes that constitute a risk for PCa and should be considered in the development of PCa biomarkers and cancer screening programs." (PMID 36321189, 2023). "This regulation by redox copper may also explain previous findings of increased CP expression in several cancers, where the intracellular copper level is higher in a redox compromised environment, such as in GB." (PMID 35918659, 2022). "Since CBD plus PPD themselves have direct and potent antitumor action, CP-liposomes may exert expectant positive effects in cancer cachexia improvement, alone or in combination with other antitumor strategies." (PMID 35893789, 2022). "Moreover, CDH2, CP and TF were low expressed in primary cancer than normal tissues, but highly expressed in metastatic liver cancer." (PMID 34422629, 2021).
cancer (continued). "In addition, the anti-cancer and anti-metastatic action of CP was further confirmed by in vivo and ex vivo experiments." (PMID 34168559, 2021). "It was found that CAV-1 was one of the largest nodes based on the “Degree > 100”, indicating that CAV-1 might play a crucial role in the anti-cancer efficacy of CP." (PMID 34168559, 2021). "In addition, compared to liver metastatic cancer tissues, CP, HP, TF, and SERPINA5 were upregulated in normal liver tissues, while the expression CDH2 and SPARCL1 did not exhibit significant differences between the two tissues." (PMID 34422629, 2021). "In contrast, CP administration decreased Cav-1 to subsequently promoted the ubiquitination-activated proteasome degradation of β-catenin, resulting in the suppression of cancer metastasis." (PMID 34168559, 2021). "While our previous study demonstrated CP’s chemotherapeutic properties (as a suppressing agent) to eradicate cancer in vitro, the present study focused on its chemopreventive activity (as a blocking agent) to prevent the initial steps of hepatocarcinogenesis in vivo." (PMID 34299510, 2021). "The combination of the haptoglobin, ceruloplasmin and C6 did not yield a better diagnostic efficacy for low grade cancer patients compared to individual biomarker alone (data not shown)." (PMID 32620920, 2020). "Ceruloplasmin is an acute phase protein; its synthesis and secretion can be significantly increased due to inflammatory processes, infection, diabetes, cardiovascular diseases, angiogenesis, pregnancy, and cancer." (PMID 33287452, 2020). "The ADAPT CP is relevant to all cancer types and cancers of any stage." (PMID 30404619, 2018). "Ceruloplasmin has also been reported to be related to several types of cancers." (PMID 28423673, 2017). "As the hypoxic response and regulation of iron metabolism are tightly interconnected, HIF1A may be involved in regulating genes that maintain iron homeostasis, e.g., transferrin, TFR1, ceruloplasmin, and heme oxygenase 1 in cancer." (PMID 26560875, 2016). "We further investigated the expression pattern of CP in human cancer cells." (PMID 24676332, 2014). "SP90-LD accumulated in the endosomes of cancer cells to a much greater extent than CP-LD." (PMID 23776619, 2013). "Thus, in clinical trials the first goal of anti-cancer copper reduction is to reduce ceruloplasmin levels to 20% of the patient’s normal baseline." (PMID 24013775, 2013). "Western blot analysis of CP vs. NP media confirmed overexpression of AGR2 protein in cancer." (PMID 20021671, 2009). "The rise in serum copper may be due to increased turn over of ceruloplasmin in the serum of carcinoma patients." (PMID 17040577, 2006). "Ceruloplasmin could indirectly interact with cancer cells through a shared affinity with albumin for myeloperoxidase, followed by albumin binding FcRn receptors on cancer cells." (PMID 36546919, 2022). "Hence, we conclude that Cur, CP, Au-C, and Au-CP (10–30μg/mL) selectively target the cancer cells." (PMID 35216264, 2022). "Thus, the aberrant expression of ceruloplasmin has been reported in certain cancers." (PMID 34413268, 2021). "Taken together, our study not only highlights the novel function of CP formula in suppressing metastasis of HBV-associated HCC, but it also addresses the critical role of Cav-1 in mediating Akt/GSK3β/β-catenin axis to control the late-phase of cancer progression." (PMID 34168559, 2021). "A new technology for manipulating expression levels of Geminin during a specific period and also at a specific level, i. e., CP-Geminin, could help further elucidate the role of Geminin in stem cells and cancer cells, and could also provide a new tool for controlling their activity." (PMID 27195810, 2016). "Examples of abundant multi-cancer-target proteins absorbed by HBPE-NPs (VS5) included pregnancy zone protein, ceruloplasmin, and TSP-1." (PMID 36546919, 2022).
cancer (continued). "Briefly, Cell-Tracker-Deep-Red-labeled NK cells were pre-treated with different aptamers (PD-L1-apt, CD16-apt, CmutP-bi-apt, CPmut-bi-apt, or CP-bi-apt) for 30 min and then co-incubated with CFSE-labeled cancer cells." (PMID 35228895, 2022). "In the CP+ group, FC between the right DLPFC and the right ACC was positively correlated with the duration of cancer pain (r = 0.451, p = 0.035)." (PMID 36072897, 2022). "Long noncoding RNA LINC00176 positively upregulates the expression of ceruloplasmin by recruiting transcription factor BCL3, a proto-oncogene in cancer." (PMID 34413268, 2021). "Ethanolic extract of CP, CP-isolated xanthone and quercetin have been reported to attenuate the expression of NF-κB and STAT3 in several cancer cell lines." (PMID 34299510, 2021). "Results show that SPARCL1, CDH2, CP, HP, TF and SERPINA5 were all significant downregulated in cancer tissues (p < 0.05)." (PMID 34422629, 2021). "Taken together, the results of the current study reveal that CP elevation contributes to a decrease of Fe2+ and followed by HIF-2α activation via PHDs and angiogenesis, which in turn supports cancer growth and metastasis." (PMID 32708433, 2020). "Other molecules, such as CP, CERLD2, CTSD, HSPA5, HTR3A and TUBB2C, are also frequently up-regulated in cancer." (PMID 28056051, 2017). "As a result, we found 3 novel candidate genes (CP, SCEL, and MUC16), having positive coefficients with a log2 ratio >1 for advanced T, N stage and perineural invasion cancer tissue." (PMID 28423673, 2017). "CP, SCEL, and MUC16 had positive coefficients with a log2 ratio >1 for advanced T, N stage and perineural invasion cancer tissue." (PMID 28423673, 2017). "Ceruloplasmin has oxidase activity and is related with the host acute phase responses and antioxidant defense in cattle so, its level might be enhanced during inflammation, tissue insult, certain malignant tumors and oxidative stress to quench the free radicals, produced during oxidative stress." (PMID 23981231, 2013). "Thus, like CP-dn-ATF5, Bpep and Dpep show both efficacy and apparent safety in animal cancer models." (PMID 36831248, 2023). "After these findings, different forms of d/n ATF5, such as cell-penetrating d/n-ATF5-recombinant peptide (CP-d/n-ATF5-RP) and cell-penetrating d/n-ATF5-synthesized peptide (CP-d/n-ATF5-S1), were designed and investigated in various cancer types with promising results." (PMID 35806136, 2022). "A majority of cuproptosis-related genes like CP, MT1E, MT1F, MT1X, VEGFA, and PDK1 were expressed significantly higher on cancer cells, indicating that cuproptosis might occur mainly on cancer cells." (PMID 36211378, 2022). "Various biological approaches, including AAV-mediated Nm23-H1 gene transfer, CP-Nm23-H1 transduction, and MPA-induced Nm23-H1 overexpression, were tried, and they were successful in increasing Nm23-H1 expression and suppressing cancer metastasis to varying degrees." (PMID 33753879, 2021). "Additionally, miR-145-5p directly targets ceruloplasmin expression, and increased ceruloplasmin contributes to activation of the PHD/HIF-2α/VEGF-A axis to facilitate cancer growth and metastasis in LUAD." (PMID 34413268, 2021). "The proliferation of H1563 cancer cells was not significantly different between the knockdown CP group and the control group after 72 h incubation, as determined by both Water Soluble Tetrazolium Salts (WST-1) and Bromodeoxyuridine (BrdU) incorporation." (PMID 32708433, 2020). "Although we found a tendency for increased ceruloplasmin expression in advanced T stage cancer with perineural invasion, that finding did not achieve statistical significance." (PMID 28423673, 2017). "Inhibition of proteasome CT-L activity was initially pursued as a therapeutic strategy for the treatment of cancers with highly proliferative and proteasome-dependent cells; however, current FDA-approved proteasome inhibitors lack selectivity between the cP and iP." (PMID 29182146, 2017).
cancer (continued). "Although the Cu to ceruloplasmin ratio is not significantly altered, Cu and ceruloplasmin levels are increased significantly in the cancer patients compared to controls." (PMID 26356671, 2015). "In both cell lines, CP increased the antiproliferative effects of all the drugs in a synergistic way, in particular at high effect levels (GI75, GI90) that represent the most therapeutically relevant conditions for cancer therapy." (PMID 24980813, 2014). "However, the biological significance of ceruloplasmin dysregulation in cancer cells has not been completely verified and remains controversial." (PMID 34413268, 2021). "Interestingly, ROS levels were decreased and maintained in hypoxic and normoxic cancer cells, respectively, by Mito-CP but not Dec-TPP+, therefore preventing any adaptive signaling." (PMID 28426671, 2017). "Interestingly, recent investigations revealed that certain tissues and some cancer cells carry non-standard types of 20S proteasomes (referred to as hybrid or intermediate proteasomes), which contain mixed assortments of cP and iP catalytic subunits, such as β1i-β2-β5i2–6." (PMID 30858500, 2019). "Cancer’s disrupted criticality cascade parallels recent findings, where EGF stimulation failed to activate the Maxwell’s demon-like function of CP genes." (PMID 40943346, 2025).
neurodegenerative disease (27 papers, 2014 to 2026). A disorder of the central nervous system characterized by gradual and progressive loss of neural tissue and neurologic function. "Brain iron accumulation and reduced CP activity have been shown to be associated with neurodegenerative diseases." (PMID 40898358, 2025). "CP encodes a metalloprotein, which has been considered neuroprotective in neurodegenerative diseases." (PMID 33123575, 2020). "Disturbances in ceruloplasmin homeostasis have been linked to other neurodegenerative diseases, and to neuropathic pain in the constriction injury rat model of neuropathic pain.." (PMID 25144566, 2014). "CP deficiency affects neuronal projection extension, synaptic signal transmission, and cell mRNA translation and is closely related to the occurrence of neurodegenerative diseases." (PMID 40511628, 2026). "Additionally, previous studies have found that CP plays an important role in the metabolism and development of neural tissues, and the deficiency or functional impairment of ceruloplasmin is a typical feature of various neurodegenerative diseases." (PMID 38966086, 2024). "The protein ceruloplasmin, which is an enzyme that functions as a copper transporter and antioxidant protein, decreased significantly with age, which would be expected and, interestingly, a decrease in this enzyme is associated with neurodegenerative diseases." (PMID 32157596, 2020). "In particular, we focus on mitochondrial oxidative respiration via complex 4 and ceruloplasmin for iron homeostasis, and how this is similar and possibly central to neurodegenerative diseases in general." (PMID 39416952, 2024). "Previous studies have shown that CP plays a key role in the prevention of neurodegenerative disease and free radical damage." (PMID 36443285, 2022). "For related reasons, it was proposed that CP may play a protective role against neurodegenerative diseases." (PMID 41012571, 2025). "Previous reports have suggested a protective role of ceruloplasmin in neurodegenerative diseases." (PMID 41402737, 2025). "CP-AMPAR inhibition may serve as a strategy for the intervention of neurodegenerative diseases in which calcium homeostasis was disturbed and γ oscillation was impaired." (PMID 37386056, 2023). "Fourth, CP-AMPARs increase in neurodegenerative disease models, but NMDARs decrease, although in a few cases they may also increase, during neural degeneration, strongly suggesting more persistent effects of excitotoxicity from CP-AMPARs." (PMID 34483848, 2021). "A recent preprint suggests that SARS-CoV-2 induces amyloid aggregation of several proteins involved in neurodegenerative diseases such as APLP1, ApoE, clusterin, α2-macroglobulin, PGK-1, ceruloplasmin, nucleolin, 14–3-3, transthyretin, and vitronectin." (PMID 36362302, 2022).
cardiovascular disease (17 papers, 2012 to 2025). "In their study, serum CP levels were reported to be an independent risk factor for cardiovascular diseases." (PMID 33096845, 2020). "It is elevated in acute and chronic inflammatory states and elevated plasma CP is also associated with increased cardiovascular disease risk." (PMID 23592955, 2013). "Both CRP and ceruloplasmin are established as markers of cardiovascular disease severity and future cardiovascular events, where ceruloplasmin has been shown to be a better predictor of long-term cardiovascular disease risk compared to CRP." (PMID 35413834, 2022). "Prospective studies have showed that serum CP may be an independent risk factor for cardiovascular disease." (PMID 33096845, 2020). "We found changes in copper were negatively associated with changes in fasting apoCIII, a lipoprotein implicated as a cardiovascular disease risk factor, and ceruloplasmin ferroxidase activity was negatively associated with increases in post-meal glucose, insulin, and lactate responses." (PMID 32854403, 2020). "The elevated serum CP concentrations observed in SSc are also indicative of increased inflammation and oxidative stress, as CP is an established positive acute phase reactant related to cardiovascular disease." (PMID 32630589, 2020). "Ceruloplasmin has also been reported to be an acute-phase protein related to various acute inflammatory conditions, including injury, tumors, and cardiovascular disease." (PMID 23505556, 2013). "Cardiovascular diseases are accompanied by the elevation of several positive acute phase reactants such as CRP, serum amyloid A (SAA), fibrinogen, white blood cell count, secretory nonpancreatic phospholipase 2-II (sPLA2-II), ferritin, and ceruloplasmin." (PMID 24049653, 2012). "Cardiovascular diseases are accompanied by the elevation of several positive acute phase reactants such as C-reactive protein (CRP), serum amyloid A (SAA), fibrinogen, white blood cell count, secretory nonpancreatic phospholipase 2-II (sPLA2-II), ferritin, and ceruloplasmin." (PMID 24049653, 2012).
neurological disorders (12 papers, 2014 to 2025). "Ca2+ influx through CP-AMPARs is crucial in several forms of synaptic plasticity and has also been linked to cell death associated with neurological diseases." (PMID 24608178, 2014). "A lasting change in the prevalence of GluA2‐containing AMPARs, and hence in the fraction of CP‐AMPARs, is a feature in many maladaptive forms of synaptic plasticity and neurological disorders." (PMID 33533533, 2021). "There is a growing body of evidence implicating CP-AMPARs during the onset of synaptic pathology in neurological disorders." (PMID 27955702, 2016). "Sixth, CP-AMPARs may be considered as an early marker indicating the onset of pathological progression in neurological diseases." (PMID 34483848, 2021). "Recently, accumulating evidence supports the role of CP-AMPARs in neurological diseases." (PMID 34483848, 2021). "Furthermore, compared to patients with liver injury as the predominant issue, HLD patients with neurological disorders as the predominant issue might exhibit significantly lower serum ceruloplasmin levels." (PMID 40438368, 2025). "Copper could combine with Aβ to produce Reactive Oxygen Species, or oxidize some fat molecules into derivatives toxic to neurons, and excess copper might lead to inflammation by increasing the ceruloplasmin leading to higher risks for some neurological diseases." (PMID 36771411, 2023). "These accounts suggest that modulation in CP expression, and thus modified physiological and cellular Cu2+ homeostasis, may exacerbate the LLPS underpinnings of viral and neurological diseases." (PMID 33081049, 2020).
genetic disease (10 papers, 2014 to 2025). "Since WD is a genetic disease, the levels of ceruloplasmin of WD in the neonatal period and adulthood should be comparable." (PMID 36547381, 2022).